JAK2 (Janus kinase 2)
Diseases named in the same sentence as JAK2 in open-access papers (continued):
Sharing a sentence is not in itself a finding about the gene and the disease.
myelofibrosis (continued). "Optimization of conditioning regimens and use of JAK2 inhibitors are thought to improve engraftment rates in bone marrow transplantation for myelofibrosis." (PMID 36629680, 2023). "Optimization of conditioning regimens and use of JAK2 inhibitors are thought to improve engraftment rates in BMT for myelofibrosis." (PMID 36629680, 2023). "Ruxolitinib, a JAK2 inhibitor currently approved for myelofibrosis and polycythemia vera, demonstrated promising results in combination with TKI in increasing TKI-induced apoptosis." (PMID 37762109, 2023). "Loss of IL-1β in JAK2-mutant hematopoietic cells prevented these alterations and correlates with reduced MPN progression to myelofibrosis and osteosclerosis." (PMID 36100613, 2022). "Ruxolitinib, a JAK1/JAK2 inhibitor, is approved by the FDA for patients with intermediate- and high-risk myelofibrosis." (PMID 35773269, 2022). "RUNX1 has been identified in a JAK2 V617F-positive PV patient and post-PV myelofibrosis patients, and this alteration appears to be a sign of disease evolution and cell transformation." (PMID 35456443, 2022). "Virtual karyotyping identifies high frequencies of mosaic chromosomal alterations (mCAs), with enrichment at myelofibrosis GWAS susceptibility loci and recurrently somatically mutated MPN genes (e.g., JAK2)." (PMID 36075929, 2022). "The Janus kinase 2 (JAK2V617F) mutation is quite common in patients with polycythaemia vera, thrombocythemia, and myelofibrosis, and these patients are at risk of both arterial and venous thrombosis, hence they require long-term follow-up." (PMID 35800822, 2022). "Inhibition of IL-1β in JAK2-V617F mutant mice by anti-IL-1β antibody also reduces myelofibrosis and osteosclerosis and shows additive effects with ruxolitinib." (PMID 36100613, 2022). "The patient who progressed to myelofibrosis harbored SRSF2, TET2, and MPL mutations at CMML diagnosis and acquired a JAK2 mutation at the time of myelofibrosis transformation." (PMID 36077644, 2022). "Fedratinib, a JAK2‐selective inhibitor, has a similar role in controlling palpable splenomegaly when treating myelofibrosis." (PMID 36254250, 2022). "Here the authors show that the JAK2-V617F mutation is associated with increased expression of IL-1 in MPN patients and that loss of IL-1β in JAK2-V617F mutant hematopoietic cells reduces MPN symptoms and myelofibrosis in a mouse model." (PMID 36100613, 2022). "Two JAK2 inhibitors, ruxolitinib and fedratinib, have been FDA approved for patients with intermediate and high-risk myelofibrosis, while ruxolitinib is also approved for hydroxyurea intolerant PV patients." (PMID 35082276, 2022). "Ruxolitinib, a selective JAK1/JAK2 inhibitor, significantly alleviates palpable splenomegaly, ameliorated debilitating myelofibrosis‐related symptoms, and improved OS compared with placebo." (PMID 36254250, 2022). "Myelofibrosis cases with high-frequency JAK2 mCAs have marked reductions in measured telomere length – suggesting a relationship between telomere biology and myelofibrosis clonal expansion." (PMID 36075929, 2022). "Vigilant blood count monitoring is warranted following the JAK-2 diagnosis, with potential subsequent bone marrow sampling, due to suspected malignant transformation or development of myelofibrosis." (PMID 35493844, 2022). "Knockout of IL-1β in hematopoietic cells of JAK2-V617F mice reduces inflammatory cytokines, prevents damage to nestin-positive niche cells and reduces megakaryopoiesis, resulting in decrease of myelofibrosis and osteosclerosis." (PMID 36100613, 2022). "The aim of study was to evaluate the PDL1 mRNA and JAK2 mRNA level in molecularly defined essential thrombocythaemia (ET) patients (pts) during disease progression to post-ET- myelofibrosis (post-ET-MF)." (PMID 36266510, 2022). "The safety profile of the novel oral JAK2/IRAK1 inhibitor pacritinib in patients with cytopenic myelofibrosis was described in the Phase 2 PAC203 and Phase 3 PERSIST‐2 studies." (PMID 36467816, 2022).
myelofibrosis (continued). "Using genetic and pharmacological approaches, we show that IL-1β inhibition reduced myelofibrosis in a preclinical JAK2-V617F MPN mouse model." (PMID 36100613, 2022). "Genetic deletion of IL-1β from JAK2-V617F mutant cells, or pharmacological inhibition of IL-1β are effective in reducing myelofibrosis and osteosclerosis in a preclinical mouse model of MPN." (PMID 36100613, 2022). "Pacritinib is an oral JAK2/IRAK1 inhibitor that was recently approved in the United States in February 2022 for patients with myelofibrosis (MF) who have a platelet count below 50 × 109/L." (PMID 36467816, 2022). "Fedratinib (Fed) is a marketed drug for the treatment of primary and secondary myelofibrosis, targeting selective JAK2 tyrosine kinase inhibitors." (PMID 34361644, 2021). "The addition of navitoclax to traditional JAK2 inhibitors in patients with myelofibrosis is demonstrating encouraging results in patients who are refractory or are relapsing on prior treatment therapy." (PMID 34667663, 2021). "The efficacy of the JAK1/JAK2 inhibitor ruxolitinib in reducing spleen size and systemic symptoms, in myelofibrosis, has been established." (PMID 34017327, 2021). "Ruxolitinib is a widely used drug in PV and myelofibrosis patients where it must be imported in the intracellular compartment in order to block JAK2 phosphorylation." (PMID 33805426, 2021). "Fedratinib (SAR302503, TG101348) is a selective Jak2 inhibitor which has been studied in myelofibrosis and was approved by the FDA in 2019." (PMID 34771633, 2021). "TG101209, a small-molecule JAK2-selective inhibitor, has better JAK2 targeting to primary myelofibrosis than ruxolitinib." (PMID 34588425, 2021). "We used the JAK1 and JAK2 inhibitor ruxolitinib, which is approved for the treatment of myelofibrosis, polycythemia vera and acute graft-versus-host disease, where it primarily exerts cytoreductive and antiproliferative effects." (PMID 34769079, 2021). "Fedratinib is a JAK2/FMS-like tyrosine kinase 3 (FLT3) inhibitor that received FDA approval for the treatment of myelofibrosis." (PMID 35056105, 2021). "Fedratinib is also a JAK2 kinase inhibitor and has also been shown to reduce splenomegaly and symptom burden in 33% of patients with myelofibrosis." (PMID 34667663, 2021). "Ruxolitinib is a potent JAK1 and JAK2 inhibitor, with good safety profile, that is approved for myelofibrosis and polycythemia vera, two myeloproliferative neoplasms characterized by over-inflammation." (PMID 32814839, 2021). "Ruxolitinib is a JAK2 inhibitor and has been shown to reduce spleen volume by 35% in 41.9% of patients with myelofibrosis." (PMID 34667663, 2021). "A phase III TRANSFORM-2 trial is also ongoing, evaluating the combination of Navitoclax and ruxolitinib vs the best available therapy (BAT) in adults with relapsed or refractory myelofibrosis resistant to single-agent JAK2 inhibition." (PMID 34667663, 2021). "Then, we report a complex structure of DCLK1 kinase domain with the most potent inhibitor ruxolitinib, which has been originally developed as a Janus kinases (JAK1 and JAK2) inhibitor for treatment of myelofibrosis." (PMID 34445192, 2021). "The initial focus was on multiple myeloma but with the discovery of V617F mutation in JAK2, attention shifted to MPN and myelofibrosis in particular." (PMID 34371735, 2021). "Ruxolitinib (INCB018424) is an approved JAK (Jak2) inhibitor for myelofibrosis, with a study currently recruiting patients with HNSCC (NCT03153982)." (PMID 34771633, 2021). "Momelotinib is a JAK1/JAK2/activin receptor type-1 (ACVR1) ATP-competitive inhibitor that is being investigated in patients with myelofibrosis who have failed previous jakinib therapy (NCT01969838)." (PMID 35056105, 2021).
myelofibrosis (continued). "In this review, we investigated the value of BM, liver, and spleen imaging for diagnosis, prognostication, and response monitoring of the JAK2/CALR/MPL mutation-related MPNs (i.e. essential thrombocythemia (ET), polycythemia vera (PV), and myelofibrosis (MF))." (PMID 33879266, 2021). "The mutations that confer activation of the intracellular Janus kinase (JAK) signal transducer and activator of transcription (STAT) pathways (e.g., JAK2, V617F, and JAK2 exon 12) were identified as the most common in patients with myelofibrosis (MF)." (PMID 35008250, 2021). "Ruxolitinib, which targets JAK1/JAK2 is used in the treatment of psoriatic arthritis, AD, and several lymphoid malignancies, e.g., myelofibrosis and polycythemia vera." (PMID 34948183, 2021). "Fedratinib (INREBIC®), a Janus kinase 2 inhibitor, is approved in the United States to treat patients with myelofibrosis." (PMID 32886148, 2020). "Accordingly, ruxolitinib is the only selective JAK1 and JAK2-inhibitor approved for the treatment of myelofibrosis and aGVHD." (PMID 33489899, 2020). "TG-101348, also known as fedratinib, is a JAK2-selective inhibitor that has been approved for treating patients with myelofibrosis." (PMID 32947833, 2020). "Baricitinib and ruxolitinib, both targeting JAK1 and JAK2 which are the dominant kinases downstream of IL-6, have been approved for the treatment of myelofibrosis and rheumatoid arthritis, respectively." (PMID 33384605, 2020). "Ruxolitinib (Jakafi or Jakavi) is a licensed, orally administered JAK1/JAK2 inhibitor used to treat neoplastic diseases, particularly myelofibrosis." (PMID 32101732, 2020). "Pacritinib is a selective JAK2 inhibitor currently being studied in a Phase III clinical trial for treatment of myelofibrosis (NCT02055781)." (PMID 33521321, 2020). "The presence of constitutional symptoms impact prognostic scoring for myelofibrosis and is a key feature in therapy response in JAK2 inhibition, indicating the importance of the presence and mitigation of these physiologic experiences." (PMID 32976697, 2020). "Until the recent approval of fedratinib, a JAK2 inhibitor, ruxolitinib was the only available JAK inhibitor for treatment of intermediate- or high-risk myelofibrosis." (PMID 32198525, 2020). "Ruxolitinib, a JAK1/JAK2 tyrosine kinase inhibitor, is currently being extensively employed in MPN-associated myelofibrosis therapy, but it has little antioxidative capacity." (PMID 33114087, 2020). "Ruxolitinib (RUX) is a first-in-class oral JAK1/JAK2 inhibitor approved for the treatment of patients with myelofibrosis based on the results of two randomized clinical trials (COMFORT-I and COMFORT-II)." (PMID 32331228, 2020). "Ruxolitinib, a JAK1/JAK2 tyrosine kinase inhibitor, is currently extensively employed in MPN-associated myelofibrosis therapy." (PMID 33114087, 2020). "Fedratinib (SAR302503, TG101348) is an orally administered Janus kinase (JAK) 2-selective inhibitor that is being developed for the treatment of patients with myelofibrosis (MF)." (PMID 31444617, 2019). "Recently, FDA approved Fedratinib, a small-molecule inhibitor of JAK2, for the treatment of myelofibrosis." (PMID 31540495, 2019). "JAK2 inhibitors are clinically efficacious in myelofibrosis, a hematological disease often driven by constitutive JAK2 activation." (PMID 31139181, 2019). "Based on these premises, we evaluated pacritinib, a recent FDA-approved inhibitor of STAT3/JAK2 signaling for treating myelofibrosis." (PMID 31269723, 2019). "For instance, selective JAK2 inhibitor TG101348 attenuated myelofibrosis in a murine model of disease." (PMID 31540495, 2019). "Ruxolitinib, an orally bioavailable and selective inhibitor of Janus kinase 1 (JAK1) and JAK2, significantly reduces splenomegaly and disease‐related symptoms in patients with myelofibrosis (MF)." (PMID 30997748, 2019).
myelofibrosis (continued). "Ruxolitinib, a JAK1/JAK2 inhibitor which is used for the treatment of myelofibrosis, received approval from multiple agencies due to its ability to reduce symptoms of the disease, including splenomegaly by 35%." (PMID 30956775, 2019). "This study compared the BioMAP phenotypic profiles of 4 agents known primarily for their JAK2 inhibition that have been clinically investigated and show important clinical activity in the treatment of myelofibrosis." (PMID 31560729, 2019). "Ruxolitinib is the first JAK1/JAK2 inhibitor specifically approved for the treatment of disease-related splenomegaly or symptoms in adult patients with primary myelofibrosis." (PMID 35620778, 2018). "We investigated the therapeutic potential of ruxolitinib, a JAK1/JAK2 inhibitor that has been FDA-approved for the treatment of myelofibrosis, to treat ovarian cancer either alone or in combination with conventional chemotherapy agents." (PMID 29849942, 2018). "Ruxolitinib is a potent and selective oral JAK1 and JAK2 inhibitor that was FDA-approved in 2011 for the treatment of myelofibrosis (MF), post-polycythemia vera myelofibrosis (PPV-MF), and post-essential thrombocythemia myelofibrosis (PET-MF)." (PMID 29849942, 2018). "Momelotinib (MMB; GS-0387; CYT387) is a JAK1 and JAK2 inhibitor, with therapeutic activity in myelofibrosis (MF), in humans as well as in mice." (PMID 29515114, 2018). "Allogeneic stem cell transplantation is currently the only curative therapy for primary myelofibrosis (MF), while the JAK2 inhibitor, ruxolitinib." (PMID 29971909, 2018). "We applied Ruxolitinib, a newly discovered inhibitor of JAK1/JAK2 previously used in the treatment of myelofibrosis." (PMID 28497028, 2017). "The JAK1 and JAK2 inhibitor ruxolitinib is approved for patients with myelofibrosis and with PV resistant or intolerant to hydroxyurea." (PMID 29228564, 2017). "Ruxolitinib, a small molecule inhibitor of JAK1 and JAK2 kinases, has been approved by the FDA for the treatment of polycythemia vera and intermediate to high-risk myelofibrosis." (PMID 29082853, 2017). "The mutation leads to constitutive activation of JAK2 and contributes to deregulate JAK signaling in myelofibrosis (MF), polycythemia vera (PV), and essential thrombocythemia (ET)." (PMID 27167495, 2016). "Ruxolitinib is a selective inhibitor of JAK1 and JAK2 that is licensed to treat myelofibrosis and being evaluated in CLL." (PMID 27579615, 2016). "Along with molecular abnormalities (mutations in JAK2, Calreticulin (CALR) and MPL genes), chronic inflammation is the major hallmark of Myelofibrosis (MF)." (PMID 27304059, 2016). "Ruxolitinib is a JAK1/JAK2 inhibitor approved for the treatment of myelofibrosis, and additional JAK2 inhibitors are in clinical development." (PMID 27043212, 2016). "On the other hand, the JAK2 inhibitor Ruxolitinib has been approved for the treatment of myelofibrosis in the United States and in the European Union." (PMID 27494133, 2016). "We conducted an exploratory analysis of sequential BMF data from two phase I studies of long-term treatment with the Janus kinase 2 (JAK2) inhibitor fedratinib in patients with myelofibrosis." (PMID 26357842, 2015). "In the first case of JAK2 positive primary myelofibrosis preceding with 6 months the diagnosis of multiple myeloma, the evolution was practically simultaneous." (PMID 25914740, 2015). "Appreciation for the activation of JAK2 and the importance of the pathogenesis of myelofibrosis has led to novel therapeutic agents targeting JAKs." (PMID 26316489, 2015). "A case is described of a JAK2 V617F-positive primary myelofibrosis patient who underwent allogeneic stem cell transplantation." (PMID 26346984, 2015). "JAK2 aberrations, for instance, are found in myelofibrosis, and JAK2 inhibitors such as ruxolitinib provide significant benefit in such patients." (PMID 26224133, 2015).
myelofibrosis (continued). "Many potent JAK2 inhibitors have been developed, and some have shown clinical benefits in treatment of myelofibrosis." (PMID 24646493, 2014). "Pacritinib, a JAK2 inhibitor is in a phase III trial to treat myelofibrosis and in several phase I/II trials in other hematologic malignancies." (PMID 24199193, 2013). "And while TG101348 has also proved palliative against JAK2V617F-induced myelofibrosis, its efficacy against JAK2-translocation leukemia/lymphoma remains untested." (PMID 23372669, 2013). "The activation of JAK2 and the increased levels of circulating proinflammatory cytokines seem to play an important role in the pathogenesis of myelofibrosis." (PMID 23039051, 2012). "The discovery of the association between JAK2V617F and MPNs has facilitated the invention of new targeted treatment strategies and resulted in the development of JAK2 inhibitor drugs for patients with myelofibrosis." (PMID 24744667, 2012). "Clinical trials using JAK2 inhibitors for patients with myelofibrosis have demonstrated the effectiveness of these drugs to reduce clinical symptoms splenomegaly and to improve quality of life." (PMID 22400031, 2012). "Several JAK2 kinase domain inhibitors, that are ATP-binding competitors are in clinical trials for primary or secondary myelofibrosis." (PMID 20585391, 2010). "JAK2 inhibitors, such as ruxolitinib show remarkable clinical activity in myelofibrosis patients, irrespective of JAK2 mutational status." (PMID 40413183, 2025). "This raises the question of whether prolonged ATP deficiency in the bone marrow predisposes individuals to driver mutations in JAK2, CALR, and MPL, thereby contributing to the development of myelofibrosis." (PMID 41179685, 2025). "While no clear overall association was found, some candidate genes exhibited concordant changes in DNAm and gene expression, such as hypermethylated and downregulated ZFP36L1, linked to myelofibrosis progression and INPP5D known to be downregulated by JAK2 V617F." (PMID 40319310, 2025). "Pivotal clinicals for JAK2 inhibitors in patients with myelofibrosis." (PMID 40507313, 2025). "Even before JAK2-V617F was discovered as a genetic driver of MPN, it had been demonstrated, that forced expression of TPO via retroviral expression or hypomorphic mutants in GATA1 were sufficient to cause fibroblast activation and myelofibrosis in mice." (PMID 40140631, 2025). "Osm deficiency also protected against splenomegaly and myelofibrosis induced by JAK2 p.V617F: Osm-/- mice displayed no signs of fibrosis after more than 200 days, whereas mild to intermediate fibrosis developed in 4/7 Jak2 p.V617F+Osm+/+ mice." (PMID 41372120, 2025). "This may explain interstitial pneumonia in myelofibrosis and how treatment with JAK2 inhibitors to block the IL-6-mediated JAK2 downstream signaling pathway also blocked the final inflammatory reaction in the lung." (PMID 39659792, 2024). "Compared to ruxolitinib, lestaurtinib showed modest clinical recovery with improvement of spleen size and no improvement in bone marrow myelofibrosis and JAK2-V617F allele burden." (PMID 39091915, 2024). "MM implicates JAK1 and JAK2 genes in its pathogenesis, much like myelofibrosis does." (PMID 38319731, 2024). "Through single-cell analysis, they identified distinctive characteristics of megakaryocyte differentiation pathways in myelofibrosis, observing a marked expansion of megakaryocyte differentiation originating from uncommitted stem and progenitor cells in JAK2 V617F-driven hematopoiesis." (PMID 39682299, 2024). "A study including mass cytometry analysis identified cytokine overproduction in myelofibrosis, which might also be involved in JAK2 inhibitor persistence in MPN patients." (PMID 39104388, 2024). "Disease-modifying effects are modest with some reductions in JAK2 allele burden, but transformation to myelofibrosis and acute leukemia is not altered by ruxolitinib." (PMID 37519812, 2023).